MCL1 (MCL1 apoptosis regulator, BCL2 family member)
Diseases named in the same sentence as MCL1 in open-access papers (continued):
Sharing a sentence is not in itself a finding about the gene and the disease.
glioblastoma (continued). "miR-193a-3p, miR-512-5p, miR-153, and miR-133B also target MCL1 and are repressed via hypermethylation in AML, gastric tumors, glioblastoma, and lung cancer, respectively." (PMID 34199020, 2021). "Potential targets of gossypol in glioblastoma TS were BCL2L2 (Bcl2 like 2), MCL1 (Myeloid cell leukemia 1), APEX, and several dehydrogenases." (PMID 31658771, 2019). "In glioblastoma cells, KPNB1 depletion inactivates Mcl-1 by downregulating Mcl-1 expression and inducing expression of Mcl-1-bound BH3-only proteins, leading to the activation of Bax and Bak." (PMID 29520102, 2018). "A more detailed mosaic plot analysis of Mcl-1 and USP9x IRS shows that Mcl-1 was upregulated in more glioblastoma tissue samples and to a greater extent than USP9x." (PMID 26775694, 2016). "In the first set of experiments, we examined the expression of Mcl-1 and USP9x in astrocytoma (WHO grade III) and glioblastoma (WHO grade IV)." (PMID 26775694, 2016). "Combined treatment with L-asparaginase and TRAIL yielded a marked down-regulation of Mcl-1 and Usp9X in LN229 glioblastoma cells." (PMID 27172899, 2016). "Treatment with L-asparaginase resulted in a marked down-regulation of Mcl-1 in T98G, U251 and LN229 glioblastoma cells." (PMID 27172899, 2016). "ATF5 is highly expressed in primary brain tumors, especially in glioblastoma, and plays a key role in promoting cancer cell survival through the CREB3L2/ATF5/MCL1 pathway." (PMID 27023521, 2016). "Here, we describe a novel drug combination for the treatment of glioblastoma that consists of the orally available Bcl-2/Bcl-xL inhibitor ABT263 and the Mcl-1 inhibitor GX15-070." (PMID 26008975, 2015). "Therefore, it is essential to study the role of MCL-1 in the prognosis prediction of glioblastoma patients and to develop safer and more effective MCL-1 inhibitors for the treatment of glioblastoma." (PMID 37538176, 2023). "The XPO1 inhibitor leptomycin B (LMB) and KPT-330 consistently downregulated Mcl-1 but not Bcl-2 or Bcl-xL in a dose-dependent manner in U87 and U251 glioblastoma cells and H1299 NSCLC cells." (PMID 31113936, 2019). "In contrast, in SF188 glioblastoma cells Mcl-1 expression was not significantly affected by the combination treatment." (PMID 27172899, 2016). "Treatment of glioblastoma cells with MA led to the inhibition of GSK3 kinase, resulting in the downregulation of SRSF1/5, PTPB1, and hnRNP with decreased levels of anti-apoptotic genes such as BCL2, BCL-xL, Survivin, MCL1, and BMI1 while increased in Anxa7, a tumor suppressor gene." (PMID 39863145, 2025). "However, the relatively mature small molecule inhibitors of MCL-1 that have been studied and developed are largely not used in the treatment of glioblastomas, probably due to difficulties in crossing the blood-brain barrier." (PMID 37538176, 2023). "However, in the treatment of glioblastoma, most MCL-1 small molecule inhibitors are not applicable due to the existence of blood-brain barrier." (PMID 37538176, 2023). "It has been reported that the low rate of apoptosis in some cancer cells, including glioblastoma, ovarian cancer, CML and AML, may be contributed to downregulation of miR-153 which targets three antiapoptotic genes, Bcl-2, Mcl-1 and XIAP through binding to 3 ́UTR of their mRNAs." (PMID 36158686, 2022). "To confirm that these results are not only relevant to cell lines derived from adult glioblastomas, we probed the KNS-42 pediatric GBM cell line and following THZ1 treatment detected a suppression of Mcl-1 transcript levels as well." (PMID 32752193, 2020). "However, not all glioblastoma tissue samples expressing high Mcl-1 levels also express high USP9x levels." (PMID 26775694, 2016).
osteosarcoma (59 papers, 2009 to 2025). A usually aggressive malignant bone-forming mesenchymal neoplasm, predominantly affecting adolescents and young adults. "Elevated MCL‐1 expression is associated with osteosarcoma recurrence, whereas its downregulation sensitises osteosarcoma cells to chemotherapy." (PMID 40889216, 2025). "We found that the previously reported tumor suppressor proteins LACTB, c‐Myc, and Mcl‐1 were highly expressive in osteosarcoma and with a robust inverse correlation to patient survival outcomes." (PMID 40616392, 2025). "Previous reports have demonstrated that osteosarcoma cells treated with LDC067 also suppressed expression of MCL-1." (PMID 41360777, 2025). "A recent study showed that MAPK signaling and the expression of anti-apoptotic protein MCL1 is elevated in osteosarcoma lung metastases." (PMID 40134582, 2025). "Our findings demonstrate that imipramine not only reduces MCL‐1 expression in osteosarcoma in vitro, but also significantly inhibits its expression in vivo." (PMID 40889216, 2025). "The treatment upregulated cleaved caspase-3, cleaved caspase-9, phosphorylated H2Ax, Bax, Bak1, and cytochrome c, while downregulating survivin and Mcl-1 in osteosarcoma cells." (PMID 40535821, 2025). "We identified S68345 as a promising candidate to induce osteosarcoma cell death through inhibition of MCL-1." (PMID 39497108, 2024). "Osteosarcoma cells were extremely sensitive to dual inhibition of MCL-1 and BCL-xL, as evidenced by rapid apoptosis at low concentrations, whilst combined BCL-xL and BCL-2 antagonism had minimal impact on cell viability." (PMID 39497108, 2024). "Combining MCL1 inhibition with chemotherapy both prevented colonization and eliminated established metastases in murine models of osteosarcoma." (PMID 37676378, 2024). "Inhibition of MCL-1 also sensitized osteosarcoma cells to killing by second-line osteosarcoma treatments, particularly regorafenib." (PMID 39497108, 2024). "We therefore modeled the outcome of combining MCL-1 inhibition with agents currently used to treat osteosarcoma patients." (PMID 39497108, 2024). "Consistent with that pattern, the three osteosarcoma cell lines with the highest MCL-1 expression were the most responsive to S63845, although BCL-xL expression in this panel of cell lines failed to reflect S63845 sensitivity." (PMID 39497108, 2024). "In summary, the present study demonstrated the critical role of MCL-1 in osteosarcoma cell survival and highlighted the potential therapeutic efficacy of targeting MCL-1 in combination with regorafenib." (PMID 39497108, 2024). "Given the urgent need for new therapeutic options for osteosarcoma, particularly in patients with metastatic disease, our results support the exploration of MCL-1-targeted treatments to improve patient outcomes in this challenging cancer type." (PMID 39497108, 2024). "Niche-derived growth factors drive MAPK activity and MCL1 expression in osteosarcoma, promoting metastatic colonization." (PMID 37676378, 2024). "This suggests that osteosarcoma cells predominantly rely on MCL-1 for their survival, while BCL-xL and BCL-2 complement MCL-1 in maintaining osteosarcoma cell survival." (PMID 39497108, 2024). "In our study, the most marked difference in BH3 mimetic sensitivity by osteosarcoma cell lines was their sensitivity to MCL-1 antagonism (by S63845)." (PMID 39497108, 2024). "The precise mechanisms and selective pressures behind osteosarcoma’s dependence on MCL1 are an exciting avenue of future research." (PMID 37676378, 2024). "Another report showed combined inhibition of BCL-xL and MCL-1 was effective at inducing cell death in two osteosarcoma cell lines, whereas both drugs were relatively ineffective on their own." (PMID 39497108, 2024). "In summary, miR-4270 mainly decreased the expression of the anti-apoptotic proteins Bcl-xL and Mcl-1, whereas miR-342-5p mainly decreased that of Bcl-xL and also Bcl-2 in osteosarcoma cells." (PMID 37719019, 2023).
osteosarcoma (continued). "In osteosarcoma, dinaciclib, a pan-cyclin-dependent kinase inhibitor, induced apoptosis by suppressing the expression of MCL-1 and BCL-XL and by inducing the expression of BIM." (PMID 36849535, 2023). "In all three osteosarcoma cell lines, miR-4270 decreased Mcl-1 protein expression at different levels: by 1.4-fold in HOS cells and by 1.7-fold in MG-63 and SaOS-2 cells." (PMID 37719019, 2023). "Although Mcl-1 was a predicted target of miR-491-5p and miR-342-5p, neither miRNA significantly modulated its protein expression in osteosarcoma cells, with a maximum decrease of 1.2-fold for miR-342-5p in HOS cells and for miR-491-5p in SaOS-2 cells." (PMID 35337159, 2022). "It’s also reported that the progression of osteosarcoma was affected by circEPSTI1-miR-892b-MCL1 axis." (PMID 33534779, 2021). "As a target of miR-26a in human osteosarcoma cells, the expression of MCL1 ought to be suppressed by miR-26a." (PMID 33816494, 2021). "While the exact molecular mechanism of TOPK inhibition in osteosarcoma is unclear, we report a marked decrease in the antiapoptotic proteins Mcl‐1 and Survivin alongside increased apoptotic cleavage of PARP." (PMID 34115928, 2021). "Taken together, these results identify MCL1 as a direct target of miR-26a in human osteosarcoma cells, whereby miR-26a decreases MCL1 expression." (PMID 33816494, 2021). "In conclusion, together with results from clinical samples and several in vitro evidence, this study identifies miR-26a as a novel regulator of MDR in human osteosarcoma cells, in which the targeted expression of MCL1 is an important mechanism." (PMID 33816494, 2021). "For this purpose, we overexpressed MCL1 in osteosarcoma MDR cells, which were simultaneously enforced to express miR-26a." (PMID 33816494, 2021). "SiRNA-mediated knockdown of MCL-1 promoted apoptosis of osteosarcoma cells by increasing their sensitivity toward the anti-cancer drug, doxorubicin." (PMID 31620362, 2019). "Our results demonstrate that LicA induced osteosarcoma cell mitochondrial dysfunction through a decrease in the expression of Bcl-2 and Mcl-1 and an increase in the expression of Bax." (PMID 31739642, 2019). "Resistance to chemotherapy, likely a consequence of the overexpression of anti-apoptotic BCL-2 family members – including MCL-1, along with a high rate of metastasis are common problems encountered in osteosarcoma patients." (PMID 29805751, 2018). "We found that SaOS-2, SJSA-1, and 143B osteosarcoma cell lines have significantly increased MCL-1 mRNA levels when compared to MSC." (PMID 29805751, 2018). "To determine if changes in E2F1 and MCL-1 proteins participate in the reduced viability that we observe in osteosarcoma cell lines following flavopiridol treatment, we analyzed the expression of these proteins." (PMID 29805751, 2018). "In osteosarcoma, miR-133a not only targets MCL1 but also BCLxL where its expression level is commonly down-regulated." (PMID 29361709, 2018). "To evaluate the effect of MCL1-targeted miRNAs in the chemosensitivity of human osteosarcoma cells, we introduced exogenous miR-15a, miR-16, miR-29a or control miRNA into SaOS-2 and MNNG/HOS cells." (PMID 27356624, 2016). "miRNA-133a, downregulated in osteosarcoma, suppresses proliferation and promotes apoptosis by targeting Bcl-xL and Mcl-1." (PMID 32309578, 2016). "The siRNA-mediated knockdown of MCL1 expression sensitized human osteosarcoma cells to common chemotherapeutic agents." (PMID 27356624, 2016). "We also found that upregulation of microRNA-29 targeting MCL1 via virally induced transcriptional factor E2F-1 activation was critical for the enhancement of chemotherapy-induced apoptosis in osteosarcoma cells." (PMID 27356624, 2016). "OBP-301 inhibits anti-apoptotic myeloid cell leukemia 1 (MCL1) expression, which in turn leads to chemosensitization in human osteosarcoma cells." (PMID 27356624, 2016).
osteosarcoma (continued). "Our findings suggest that miR-29-mediated suppression of anti-apoptotic factor MCL1 was a critical factor for the enhancement of chemosensitivity in human osteosarcoma cells." (PMID 27356624, 2016). "Evidence shows that BCL-xL and MCL-1 are targets of miR-133a, and over-expression of miR-133a inhibits cell proliferation and promotes cell apoptosis of osteosarcoma cell lines through decreasing BCL-xL and MCL-1 expression." (PMID 24391788, 2013). "In addition, TF3 increased the levels of phosphorylated histone H2Ax, Bax, Bak1, and cytochrome c, while reducing the levels of Mcl-1 and survivin in osteosarcoma cells." (PMID 40535821, 2025). "Both ERK activity and MCL1 expression are found to be elevated in early mouse osteosarcoma metastases, indicating a trend toward increased proliferation and anti-apoptotic signaling in osteosarcoma tumor cells." (PMID 40374715, 2025). "Confirming expression of MCL1 in human osteosarcoma metastases and spontaneous canine osteosarcoma metastases argues for further testing of MCL1 inhibitors in canine cell lines and eventually canine clinical trials as a vetting process prior to human clinical trials." (PMID 37676378, 2024). "As pet dogs often develop highly metastatic osteosarcoma, and as integrative trials present opportunities to accelerate translation, we also wanted to confirm that metastatic canine osteosarcomas also show prominent MCL1 expression." (PMID 37676378, 2024). "Indeed, recent studies have shown that some osteosarcoma cell lines express more MCL1 than other BCL2 members." (PMID 37676378, 2024). "We demonstrated that osteosarcoma cell lines could be killed through inhibition of MCL-1 combined with BCL-2 or BCL-xL antagonism." (PMID 39497108, 2024). "In this study we showed that inhibition of MCL-1 (with S63845) combined with inhibition of BCL-2 (with ABT-199) or BCL-xL (with A-1331852) consistently reduced the viability of osteosarcoma cells in vitro when drugs were applied at low micromolar concentrations." (PMID 39497108, 2024). "Together, our results highlight the importance of MCL-1 in osteosarcoma cell survival and present a potential therapeutic avenue that may improve metastatic osteosarcoma patient outcomes." (PMID 39497108, 2024). "Importantly, we found that inhibition of MCL-1 with the BH3-mimetic S63845 combined with regorafenib significantly prolonged the survival of mice bearing pulmonary osteosarcoma metastases." (PMID 39497108, 2024). "Further analyses using cells from more osteosarcomas will be required to determine the feasibility of predicting responsiveness of individual tumors to BH3-mimetics through measuring expression levels of BCL-2 family members like MCL-1 and PUMA." (PMID 39497108, 2024). "Further illumination of this and other upstream regulators of MCL1 and its potential additional roles in osteosarcoma beyond promoting survival in the metastatic niche may be a rich vein of future research." (PMID 37676378, 2024). "Although osteosarcoma cells were highly sensitive to combined antagonism of MCL-1 and BCL-xL, dual targeting of these proteins can be hepatotoxic, which could complicate clinical translation of this finding." (PMID 39497108, 2024). "Furthermore, by inhibiting MCL-1, we observed significant cooperation with regorafenib, both in vitro and in vivo, improving survival outcomes in mouse models of osteosarcoma metastasis." (PMID 39497108, 2024). "The miR-320a/MCL1 axis mediates the doxorubicin resistance of osteosarcoma." (PMID 35444548, 2022). "Moreover, the increased expression of SNHG12 promoted the development of doxorubicin resistance through the SNHG12/miR-320a/MCL1 axis in osteosarcoma cells." (PMID 35592674, 2022). "Thus, a critical mechanism by which miR-26a negatively regulates MDR in human osteosarcoma is through targeting and suppressing MCL1 expression." (PMID 33816494, 2021).
osteosarcoma (continued). "Furthermore, by predicting the targets of miR-26a, we reveal that miR-26a directly targets and decreases MCL1 expression in osteosarcoma cells." (PMID 33816494, 2021). "We next conducted dual-luciferase reporter analysis to verify whether miR-26a directly targets the 3′-UTR of MCL1 in human osteosarcoma cells." (PMID 33816494, 2021). "We asked whether miR-26a-decreased MCL1 expression contributes to the reversed MDR in human osteosarcoma cells." (PMID 33816494, 2021). "MCL1 is well established as an anti-apoptotic molecule which could regulate chemoresistance in multiple cancer types, including osteosarcoma." (PMID 33816494, 2021). "Lastly, the reverse proof that enforced MCL1 expression markedly restores miR-26a-reversed MDR in osteosarcoma MDR cell lines demonstrates that the targeted expression of MCL1 is a critical mechanism by which miR-26a negatively regulates MDR in osteosarcoma." (PMID 33816494, 2021). "Moreover, doxorubicin resistance in osteosarcoma was promoted by SNHG12 via targeting miR-320a to upregulate myeloid cell leukemia 1 (MCL1)." (PMID 33124951, 2020). "Moreover, BETd-260 substantially inhibited the expression of anti-apoptotic Mcl-1, Bcl-xl while increased the expression of pro-apoptotic Noxa, which resulted in massive apoptosis in osteosarcoma cells within hours." (PMID 31653826, 2019). "Tumor progression-associated proteins (VEGF, MMP-9, Cyclin-D1, C-FLIP, MCL-1, and XIAP) may serve as therapeutic targets for inhibition of osteosarcoma progression." (PMID 31238539, 2019). "Our current results also presented that both PD98059 (MEK/ERK pathway inhibitor) and miltefosine (AKT inhibitor) both inhibit the expression of tumor progression-associated proteins (VEGF, MMP-9, Cyclin-D1, C-FLIP, MCL-1, and XIAP) in osteosarcoma U-2 OS cells in vitro." (PMID 31238539, 2019). "Thus, virus-mediated telomerase-specific targeting of MCL-1 expression offers a promising strategy to improve the clinical benefits of conventional chemotherapy in osteosarcoma patients." (PMID 27356624, 2016). "The present study demonstrated that a tumor-specific replication-competent oncolytic adenovirus OBP-301 induced miR-29 upregulation via E2F1 activation, which resulted in suppression of anti-apoptotic BCL2 family protein MCL1 in chemotherapy-resistant human osteosarcoma cells." (PMID 27356624, 2016). "Our data suggest that replicative virus-mediated tumor-specific MCL1 ablation may be a promising strategy to attenuate chemoresistance in osteosarcoma patients." (PMID 27356624, 2016). "Virally triggered MCL1 depletion may be a novel, promising strategy to overcome chemoresistance in human osteosarcomas." (PMID 27356624, 2016). "Furthermore, treatment with CDDO-Me inhibited the Stat3 pathway with decreased levels of Bcl-xL, survivin and Mcl-1 proteins in multi-drug resistant osteosarcoma cell lines." (PMID 26244918, 2015). "MCL-1 mediates the inhibition of osteosarcoma pathogenesis by miR-133a." (PMID 26036638, 2015). "The decrease expression of anti-apoptotic molecules BCL2L2 (Bcl-w) and MCL-1 may contributes to the increasing apoptosis of osteosarcoma cells." (PMID 24391788, 2013). "Targeting MCL1 in osteosarcoma shows therapeutic potential and may be a viable strategy for canine and human clinical trials, as dogs are an established model of spontaneous osteosarcoma and their MCL1 protein is highly homologous to humans." (PMID 37676378, 2024). "Finally, we determined whether the cooperation we observed between the MCL-1 inhibitor S63845 and regorafenib in vitro could also inhibit osteosarcoma lung metastases growth in vivo." (PMID 39497108, 2024). "Canine clinical trials may be an appealing first step in testing MCL1 inhibition in osteosarcoma because AZD5991 and other MCL1 targeting drugs bind to canine MCL1 and human MCL1 with similar affinity, likely due to the fact that MCL1 is nearly identical in these species." (PMID 37676378, 2024).